CD68 (CD68 molecule)
Diseases named in the same sentence as CD68 in open-access papers (continued):
Sharing a sentence is not in itself a finding about the gene and the disease.
tumor (continued). "We have previously shown in a relatively large clinical cohort that a high infiltration of cells expressing the macrophage marker CD68 at the tumor front in CRC results in an improved prognosis." (PMID 23077543, 2012). "Immunohistochemically, the tumor cells showed typically positive for Vimentin(27/27), CD68(13/13), and MAC387(2/2), and AAT(13/14), Lysozyme(11/12), ACT(10/12) showed positive in most cases." (PMID 22221822, 2012). "The lowest quartile of CD68-positive tumours had a substantially higher miR-92a content compared to a stepwise reduction in miR-92a levels with increasing CD68 macrophage contents indicating an inverse link between miR-92a expression and macrophages." (PMID 22563438, 2012). "Increased expression of CD68 in tumor correlated with malignancy grade (P = 0.016) and expression of Ki67 (P < 0.001)." (PMID 22554285, 2012). "Due to loss of material or low tumor cell content, 121 (84%) samples were annotated for CD163 in TS, 105 (73%) for CD163 in TN and 108 (75%) samples were scored for CD68 in both TS and TN." (PMID 22824040, 2012). "In co-variation analyses between malignancy grade and expression of the different markers in tumor, Ki67, CD68, M-CSF and TGF-beta showed statistical significance (data not shown)." (PMID 22554285, 2012). "An important finding from our previous study in the TRAMP-C1 tumor model was aggregation of CD68+ TAMs into chronic hypoxic regions after RT." (PMID 22888475, 2012). "The number of S100A9 positive cells in the tumor stroma correlated to the number of tumor infiltrating CD68 positive macrophages." (PMID 22470535, 2012). "Cox's univariate (HR) and multivariate (RR) analysis of the significant relationships between MMPs, TIMPs expression or CD68/(CD3+CD20) ratio at the tumor center or at the invasive front, and relapse-free survival." (PMID 23300781, 2012). "The tumor cells in the present case apparently revealed positive expression of specific histiocytic markers, such as CD68 (KP-1), and lysozyme." (PMID 23075171, 2012). "It was shown that the number of CD68 positive staining macrophages was closely associated with TNM stage (P = 0.001), metastasis to lymph node (P = 0.001) and tumor invasion to pleura (P = 0.001)." (PMID 23227270, 2012). "CD45 expression correlated with tumor size (p < 0.006; r = 0.33) and tumor growth index (p < 0.002; r = 0.38), and CD68 expression also correlated with tumor size (p < 0.0001; r = 0.46) and tumor growth index (p < 0.0001, r = 0.48)." (PMID 22555941, 2012). "Increased expression of CD68 in tumor correlated significantly with malignancy grade (P = 0.016), but not DSS (P = 0.270)." (PMID 22554285, 2012). "Also, tumour-associated macrophages (CD68+) may have prognostic value in oesophageal cancer." (PMID 22240784, 2012). "Immunohistochemically, the tumor cells showed positive for vimentin and CD68, while stains for CK, CK8/18, CD35, CD21, CD1a, S-100, HMB45, MelanA, SMA, LCA were all negative." (PMID 22221822, 2012). "The tumor expression levels of CD68, another macrophage marker, indicated the long-time survivors to express the lowest levels of CD68+ macrophages." (PMID 22190968, 2011). "Backward variable selection in a Cox model verified tumour size and histology, and the three molecular markers CD68, Gas6, and Notch3, as relevant factors." (PMID 21794149, 2011). "Number of macrophages as detected by brown positive CD68 immunostaining is significantly less in CR CT-2A tumor than in AL CT-2A tumor." (PMID 21479220, 2011). "In our previous study, we found that in paediatric solid tumours, including ESFTs, the predominant infiltrating cells were CD68+ macrophages, which accumulated in these tumours at the areas of necrosis." (PMID 22084725, 2011). "The CD68+ macrophages were distributed in the tumor stroma and parenchyma, even in the grade I OSCC." (PMID 24213108, 2011).
tumor (continued). "In summary, indicators of tumour and host biology such as Gas6, CD68 and Notch are helpful for improving the prediction of prognosis after NSCLC, but MMP2 and Cox2 were of no clinical value in the present study." (PMID 21794149, 2011). "Our study demonstrated an association between CD3ε, CD25, CD68, and ICAM-1 mRNA levels in BCC tumor biopsies and the risk for subsequent tumors." (PMID 21980389, 2011). "In the current study, the immunohistochemical analysis demonstrated that although no positive staining for CD68 was detected in normal oral mucosa, CD68+ cells were observed in all grades of tumor specimens." (PMID 24213108, 2011). "Immunohistochemical staining with a rat anti-MΦ monoclonal antibody [RM0029-11H3], anti-F4/80, and anti-CD68 showed that the number of MΦ in tumor tissues was significantly lower than that in control tissues (p < 0.001)." (PMID 21813021, 2011). "The associated osteoclast-like giant cells were abundant, evenly distributed within the tumor and showed strong positivity for CD68." (PMID 21559205, 2011). "Without adjusting for age or gender, analyses showed that patients with low CD68 mRNA expression in biopsies had significantly shorter tumor-free periods (p = 0.003)." (PMID 21980389, 2011). "The number of CD45+ and CD68+ cells was markedly increased in the tumor tissues of HFD-fed mice, indicating increased infiltration of these immune cells into tumor tissues, which possibly increased tumor angiogenesis." (PMID 21834963, 2011). "CD68-positive cells were mostly in apparent direct contact with or immediately adjacent to tumor cells lining the invasive front." (PMID 20141634, 2010). "Even in cases with no obvious PTL inflammation, the higher the number of CD8+, FOXp3+ and CD68+ cells relative to the number of tumor buds (ratio of immune cells-defenders /tumor budding cells-attackers), the more favorable the impact on patient survival." (PMID 21317460, 2010). "Although the presence of CD8+ cells among patients with MSI-H tumors does not seem to influence outcome, the ratio between CD8+, FOXp3+ and CD68+ cells and the presence of tumor budding has an independent effect on prognosis in both MSS and MSI-H cancers." (PMID 21317460, 2010). "Positive CD4, CD3, CD8, CD68 and Foxp3 cells were detected in 33/33 (100%) tumor samples and their mean number were similar between the two patient groups." (PMID 20591136, 2010). "In both subjects, prediction of co-receptor usage was consistent with CD68/p24 staining of tumor tissues." (PMID 19997510, 2009). "Patients with high versus low stromal CD68+/FoxP3+ cell ratios in primary tumour displayed median survivals of 32 and 55 months, respectively (p = 0.008)." (PMID 19732435, 2009). "As angiogenic factors are also produced by tumour-associated macrophage (TAM), we have enumerated the number of CD68-positive cells and correlated their number with the number of CD105- and CD31-positive stromal vessels." (PMID 19352388, 2009). "IHC demonstrated CD68+ macrophages clearly as dark brown-stained nucleated cells in both the tumour islet and stroma." (PMID 18283317, 2008). "Immunohistochemistry was used to identify CD68+ macrophages in the tumour islet and surrounding stroma." (PMID 18283317, 2008). "Cells that were positive for CD68 occurred in the same area of the tumour material and, as expected, displayed similar morphological characteristics as IL-17-positive cells." (PMID 19014637, 2008). "We used two different markers to identify tumor-infiltrating macrophages: CD68 as a less specific lysosomal marker and CD163 as a marker more specific for macrophages." (PMID 18047662, 2007). "In the present case, the IHC is positive for EMA and desmin, which are smooth muscle markers and CD-68 is an inflammatory marker, suggesting the tumor to be IMT." (PMID 16212671, 2005).
tumor (continued). "Another important observation of the present study is the clear association between the expression of TP and the accumulation of CD68 positive macrophages (TAMs) in the tumour supporting stroma." (PMID 11986782, 2002). "Additionally, mIHC staining revealed an increase in M2-type TAMs positive for CD163 and CD68 within the tumor regions, whereas CD206 was poorly expressed, indicating that CD163 was a better marker in this scenario." (PMID 41545340, 2026). "Notably, KRTCAP2 expression showed a significant positive association with the density of infiltrating CD68+ and CD163+ tumor-associated macrophages (TAMs)." (PMID 41676149, 2026). "Microenvironmental factors such as hypoxia, extracellular matrix composition, or metabolic reprogramming could differentially regulate CD68 expression across tumor types." (PMID 40918116, 2025). "Additionally, we further explored the spatial transcriptomics data by performing spatial colocalization analysis between the CD8+ T cell marker gene (GZMB), the macrophage marker gene (CD68) and the tumour cell marker gene (CEACAM5)." (PMID 40770837, 2025). "CD68+ macrophages in STAD may exhibit M1-dominant anti-tumor activity, while in COAD, they may adopt an M2-like, pro-tumorigenic state." (PMID 40918116, 2025). "These ROIs were selected based on the presence of PanCK+ tumor regions directly adjacent to dense CD3D+ and CD68+ immune infiltrates, identified through both H&E and multiplex immunofluorescence staining, to capture tumor margins involved in immune interaction." (PMID 40776410, 2025). "The logistic model, resulting from a backward Wald stepwise elimination of variables, revealed that local invasion, lymph node and distant metastasis, and values higher than the P50 for CD68 + (p = 0.046) at the tumor center were independent prognostic factors for CSS." (PMID 39751643, 2025). "Even though CD68 expression is considered a valuable tool for the assessment of tumor grade and metastatic potential, its contribution to CRC development and drug resistance remains unknown." (PMID 40277899, 2025). "Furthermore, the regressing tumor exhibited a rise in both CD163:CD68 and FoxP3:CD4 ratios, suggesting that the inflammation driving STR was associated with an upregulation in immunosuppressive M2 macrophages and regulatory T-cells (Tregs), respectively." (PMID 40594889, 2025). "Of note, our models did not include settings with cocultured immune cells, suggesting that CD68 may play a distinct role within ACC tumor cells themselves." (PMID 41310103, 2025). "Second, differences in cell type composition within tumor samples could contribute to these variations - while CD68 is primarily a macrophage marker, its expression may also occur in other myeloid cell populations that differ in proportion across cancer types." (PMID 40918116, 2025). "M1-like macrophages (CD68+CD163low) play an antitumoral role, whereas M2-like macrophages (CD68+CD163high) usually have protumoral effects, are predominantly found within the tumor, and express immune-checkpoint-related molecules such as PD-L1 and TIM3, conferring an immunosuppressive TME to PCNSL." (PMID 40941006, 2025). "In contrast, CD68+ and CD163+ cells were positively associated with arginase and negatively associated with nitric oxide, suggesting immune-metabolic patterns commonly observed in the tumor microenvironment." (PMID 41573553, 2025). "Suppressive CD68+CD163+ macrophages in the tumor near normal tissue were relatively abundant." (PMID 40498004, 2025). "WB results also showed down-regulated protein expression of CD68 in the tumor-bearing mice." (PMID 40761779, 2025). "Specifically, we identified higher levels of CD3+ T cells, CD20+ B cells, NK1.1+ NK cells, CD11c+I-A/I-E+ APCs, CD68+ macrophages, and Gr-1+ neutrophils by immunofluorescent staining on tumor sections from mice post BNT162b2 intratumoral injection, which was consistent with the flow cytometry data." (PMID 39743545, 2025).
tumor (continued). "In this retrospective study, we analyzed clinical data, tumor extension, cystic characteristics and immunohistochemical markers for inflammation (CD68, CD163, CD3, CD8) and proliferation (MIB-1) as potential factors influencing the EOR in 1007 surgically treated primary sporadic VS." (PMID 41044688, 2025). "They used CD68, a pan‐macrophage marker, and CD163, a marker of tumor‐associated macrophage class 2 (TAM‐2), which are considered tumor‐promoting due to their ability to facilitate tumor progression." (PMID 40736369, 2025). "Moreover, it highlighted the importance of the presence of CXCL9+CD68+ throughout tumor regions and their proximity to CD8+ T cells." (PMID 39965007, 2025). "Studies have found that high MSLN expression is associated with the epithelioid PM subtype and a high density of CD8+ T cells, CD68+ macrophages, and type I collagen fibers, whereas low MSLN expression is linked to tumor necrosis and nuclear Grade 1 (low malignancy)." (PMID 40904706, 2025). "However, the probe didn’t efficiently differentiate between the tumor-infiltrating monocytes, as indicated by the CD68 staining, which is a macrophage/monocyte marker." (PMID 39865337, 2025). "Using our IMC data, which preserved the spatial architecture of the TME, we calculated the distances between individual immune cell populations (CD4+ and CD8+ TILs, and CD68+ TAMs), as well as the distances between those immune cell populations and tumor cells." (PMID 40459946, 2025). "The proportion of CD68-positive macrophages and CD16-positive NK cells was also markedly decreased, providing compelling evidence that TOPK deficiency substantially inhibits infiltration and activity of macrophages and NK cells within tumor tissues." (PMID 40826334, 2025). "We observed CD163+ M2 TAMs only at the primary tumour periphery, with minimal infiltration into the tumour, suggesting that the CD68+ cells within the OS tumours were non-M2 myeloid lineage cell types, such as M1 TAM or osteoclasts, while M2 TAM congregate at the tumour invasive edge." (PMID 41315643, 2025). "Historically, CD68 has been utilized as an important cytochemical marker for the immunostaining of monocytes and macrophages in the histochemical examination of inflamed tissues, tumor specimens, and other immunohistopathological contexts." (PMID 40529491, 2025). "Additionally, the expression level of CD68 is generally higher in tumor tissues compared to normal tissues." (PMID 40918116, 2025). "The significant negative correlation between CD68 expression and tumor purity further supports the idea that CD68 is closely associated with immune cell infiltration rather than tumor cell density." (PMID 40918116, 2025). "Interestingly, a higher proportion of tumor‐supportive Treg cells was observed in patients with low CD68+ CAFs." (PMID 40656546, 2025). "To determine whether CXCL7 is derived from primary or acquired resistance, we examined the expression of CXCL7 and CD68 in tumor tissues before and after chemotherapy from the same patient." (PMID 40368902, 2025). "Moreover, using IF, we determined the specific topography of CD20+ tumor cells (intra-T area) and of CD68+CD86+ M1 and CD68+CSF1-R+ M2 macrophages (peri-T area) in DLBCL samples." (PMID 41415285, 2025). "In addition, mfIHC results of pre‐therapy tumor tissues also indicated that the abundance of CD68+Stat1+ cells within pan‐CK+ tumor cells or CD8+ T cells was associated with a better response to immunochemotherapy in patients with ESCC." (PMID 40995650, 2025). "Furthermore, IHC validation confirmed both the upregulation of DPP7 in tumor and its positive correlation with CD68 expression." (PMID 41208881, 2025). "In the tumor microenvironment, CD68 immunohistochemical positivity indicates macrophages." (PMID 41426308, 2025). "Furthermore, silencing TRIM47 resulted in a decrease in CD68+CD206+ cells within the tumor tissues, whereas overexpression of TRIM47 led to an increase in CD68+CD206+ cells in the same tissues." (PMID 41380966, 2025).
tumor (continued). "Moreover, tumor-associated macrophages (TAMs) exhibit functional plasticity, polarizing toward either a pro-inflammatory, antitumor phenotype (M1, CD68-positive) or an anti-inflammatory, tumor-promoting phenotype (M2, CD163-positive)." (PMID 41239536, 2025). "Interestingly, tumorous tissue contained more CD68+ cells and an increased share of ZEB1+ cells among those as compared to respective healthy tissue." (PMID 40595293, 2025). "Interestingly, high T cell infiltration was linked to high CD68+CD163+ macrophage infiltration in both subtypes, suggesting a coordinated role of these immune cells within the tumor microenvironment." (PMID 40601026, 2025). "Moreover, the ICG signal accumulates in tumor stromal regions with higher vascular density and infiltrative macrophages expressing immunosuppressive markers, including Cd68 and Spp1." (PMID 41214366, 2025). "These tumour cells are immunohistochemically positive for S-100 protein (supporting the neural origin of granular cell tumour), as well as for neuron-specific enolase, CD68, calretinin, CD57, inhibin, TFE3, SOX, CD59, PGP9.5, and vimentin." (PMID 40256332, 2025). "To further validate the changes in macrophage polyamine metabolism, we added CD68 labeling of macrophages and found that the content of C1 and C4 subpopulations of macrophages in tumor tissue also significantly increased, which is consistent with our prediction." (PMID 40390766, 2025). "Immunohistochemistry revealed tumor cells positively expressed vimentin, Cluster of Differentiation 34 (CD34), cytokeratin (CK), and CD56, while they negatively expressed insulinoma-associated protein 1 (INSM1), S100, CD68, and so on." (PMID 41244767, 2025). "The single exception was a small reduction of CD68+ cells in ICI + cis treated tumours." (PMID 40473819, 2025). "Additionally, staining with anti-CD68-antibodies was performed to distinguish tumor cells from macrophages." (PMID 39869598, 2025). "With regard to the RRS/TMB-stratified groups, the BL group had the highest level of CD68+ macrophage infiltration in the tumor center among the three groups, suggesting the overall tumor-promoting effect of macrophages in this region in patients with both low RRS and TMB." (PMID 41001426, 2025). "These crucial findings are supported by identification of increased levels of tumor-promoting CD68+CD163+ M2-like MPs, together with Rep expression, as well as increased detection of markers for oxidative DNA damage (8OHdG), most probably evoked by inflammation-driven radical formation." (PMID 40136704, 2025). "Among 121 PTC cases, 15% had CD68+ TAMs with phagocytic activity against tumor cells." (PMID 40136652, 2025). "PD-L1 and CD68 had higher IHC scores in LOW vs CIMP lesions in the intra-tumor compartment." (PMID 40682094, 2025). "Consequently, the results of the IHC staining of xenograft tumours further confirmed that the number of macrophages, especially the number of CD68+ macrophages (M2), significantly decreased in the DSG2-knockdown group." (PMID 40615400, 2025). "Furthermore, the association between high expression of CD68+CD163+ and diminished survival outcomes highlights the importance of the tumor microenvironment in disease prognosis and therapy." (PMID 40362553, 2025). "There is greater enrichment of CD68 clusters 3, 6, and 7 with tumor cells in the HIV+ group." (PMID 40459946, 2025). "However, we found statistical relevance for DFS for CD68+CD163+MPO+ cells in the epithelial compartment of tumor distant normal tissue." (PMID 40498004, 2025). "Specifically, the authors examined the status of CD3(+), CD4(+), CD8(+), CD20(+), and CD68(+) cells separately in the tumor center and the invasive front and demonstrated that increased CD3(+) T cell density at the tumor center is associated with a favorable response to neoadjuvant chemotherapy." (PMID 40243442, 2025).